OPTN (optineurin)
Diseases named in the same sentence as OPTN in open-access papers (continued):
Sharing a sentence is not in itself a finding about the gene and the disease.
tumor (continued). "Western blot analysis revealed as well that tumor tissues expressed higher levels of OPTN compared with those of tissues derived from non‐tumor liver tissues." (PMID 33600074, 2021). "We used this KO cell line to establish and exploit a mouse model of HCC to determine the effects of OPTN expression on tumor progression." (PMID 33600074, 2021). "In this model, OPTN plays a central role in regulation of TBK1 functional activity to reverse tumor stemness and drug resistance in FGβ3 cells." (PMID 32514015, 2020). "Due to the potential regulation of SUV39H2 over OPTN and the tumor-repressive activity of OPTN, we next conducted clone formation assays in the A549 cells with SUV39H2 knockdown." (PMID 30348215, 2018). "We have previously demonstrated that ubiquitylation of OPTN by tumor-suppressing E3 ubiquitin ligase, HACE1, promotes the formation of autophagy receptor complex and activates autophagy." (PMID 30519240, 2018). "HACE1, an E3 ubiquitin ligase and potent tumour suppressor, ubiquitylates optineurin which promotes its interaction with p62 and induces autophagy." (PMID 29867991, 2018). "In particular, tumors characterized by OPTN overexpression or tumor-promoting activity may be especially responsive to therapeutic interventions aimed at modulating its function." (PMID 41294799, 2025). "As an autophagy adapter protein, HACE1 prevents cellular oxidative damage and tumor progression by activating autophagy to remove toxic proteins and damaged organelles through the ubiquitination of the selective autophagy receptors p62 and OPTN." (PMID 40948788, 2025). "BECN1 had negative risk scores in two CRISPR screen datasets (Pan2018 OTI and PAN2018 Pmell), while OPTN had a negative risk score in M2 tumor-associated macrophages." (PMID 39859167, 2025). "Targeting OPTN specifically within the tumor microenvironment, using these advanced delivery systems, may allow researchers to harness its therapeutic potential without compromising normal tissue function." (PMID 41294799, 2025). "In vivo studies demonstrate that OPTN-deficient CRC cells exhibit enhanced tumor growth in immunocompetent mice, but not in immunodeficient models, highlighting its role in immune-mediated tumor control." (PMID 41294799, 2025). "Besides, platelet derived growth factor (PDGF) signaling can induce METTL3, decrease the tumor-suppressive Optineurin Gene (OPTN) protein levels and promote GSC proliferation and self-renewal." (PMID 38711100, 2024). "Importantly, OPTN has been found to be downregulated in GBM tumor samples, which has been corroborated by independent studies." (PMID 37628602, 2023). "The same study proposes that inducing OPTN expression in GBM cells could help control tumor growth, supporting a suppressive role for this gene, although the underlying mechanism remains unknown." (PMID 37628602, 2023). "Moreover, high OPTN expression was identified as an independent predictor of mortality and tumor recurrence after patients underwent surgery for HCC." (PMID 33600074, 2021). "Thus, optineurin-induced autophagy appears to represent a potential tumour suppressing pathway in some cancers." (PMID 29867991, 2018). "Additionally, to mitigate systemic side effects, a tumor-specific approach to OPTN inhibition may be considered." (PMID 41294799, 2025). "Moreover, the migration ability was significantly attenuated in OPTN‐silenced tumour cells." (PMID 35075807, 2022). "Moreover, ubiquitylation of OPTN activates selective autophagy resulting in tumour suppression." (PMID 35075807, 2022). "Mutation analysis also showed frequent alterations in PRKN (34%), OPTN (21%), PINK1 (28%), and SRC (15%), with implications for the tumor microenvironment." (PMID 39859167, 2025). "Consistent with OPTN having a tumor-suppressive role in GBM, analysis of tumor databases revealed that GBM patients with high OPTN expression have a significantly longer survival than patients with lower OPTN levels." (PMID 37242454, 2023).
tumor (continued). "As a tumor suppressor, ubiquitin ligase HACE1 ubiquitinates optineurin (OPTN) with K27 and K48 ubiquitin linkages and on multiple lysine residues of OPTN containing K193." (PMID 36646695, 2023). "Here, we demonstrated that NLRP6 acts as a scaffold protein to interact with p85α and recruit RBX1 to ubiquitinate p85α for OPTN-mediated autophagic degradation, leading to PI3K/AKT activation to enhance tumour progression." (PMID 37770465, 2023). "In conclusion, our studies demonstrate that NLRP6 acts as a scaffold protein to interact with p85α and recruit RBX1 to ubiquitinate p85α for OPTN-mediated autophagic degradation, leading to PI3K/AKT activation to enhance tumour progression." (PMID 37770465, 2023). "Western blotting was performed to analyze the expression levels of PI3K, OPTN, Akt, p-Akt, Bcl-2, Bax, caspase-3, cleaved caspase-3, ERCC1 and β-actin in the xenograft tumor tissues of mice." (PMID 35672728, 2022). "As for the autophagy receptors, MitoQ-treated tumors had an increase in p62 and OPTN levels, and a decrease in NDP52 levels as compared to the control tumor tissue." (PMID 32541677, 2020). "On one hand, OPTN has been shown to regulate NF-κB signaling by interacting with Receptor Interacting Protein 1 (RIP1), thereby suppressing excessive inflammatory responses that contribute to tumor progression." (PMID 41294799, 2025). "The subcellular localization of RRN3 in the tumor xenografts were verified by IF staining, which confirmed that the nuclear plasma-localized RRN3S199D induced a higher level of autophagy, as evidenced by both LC3 IF and OPTN IHC analyses." (PMID 41271632, 2025). "The top 5 proteins exclusively detected in tumor in ≥ 90% of the cases included CD68 (a macrophage marker), Optineurin (OPTN), Nuclear receptor coactivator 5 (NCOA5), RAP1GDS1 (Rap1 GTPase-GDP dissociation stimulator 1) and Stromal cell derived factor 2 like 1 (SDF2L1)." (PMID 36508875, 2023). "TBK1 constitutively interacts with OPTN to act as a key modulator to initiate elimination of damaged mitochondria via selective mitophagy (PINK1/Parkin-dependent mitophagy), that is involved in tumor suppression pathways." (PMID 32514015, 2020). "Furthermore, a direct interaction between the two SLRs has been demonstrated in a study showing that tumor-suppressor HACE1, a ubiquitin ligase, ubiquitinates OPTN and promotes its interaction with p62 to form the autophagy receptor complex." (PMID 30818338, 2019). "Silencing OPTN led to the acquisition of enhanced integrin-mediated adhesion and ECM stiffness-independent signaling and proliferation, attributes that may contribute to HACE1- and OPTN-induced tumor suppressor functions." (PMID 36229487, 2022). "Consequently, inhibition of OPTN may inadvertently activate compensatory survival pathways rather than induce tumor cell death." (PMID 41294799, 2025).
infection (25 papers, 2009 to 2025). The state of being infected such as from the introduction of a foreign agent such as serum, vaccine, antigenic substance or organism. "Specifically, optineurin deficiency causes a reduction of autophagic activity, which in turn leads to inadequate clearance of viral genome components from an infection." (PMID 37352136, 2023). "We also demonstrated the increased association of OPTN and TBK1 during infection, which was followed by association of OPTN and VP16." (PMID 34518549, 2021). "We generated mutant and knockdown zebrafish for two selective autophagy receptors, Optineurin and p62, and found that these have reduced anti-bacterial autophagy and are more susceptible to infection." (PMID 30818338, 2019). "Elevated OPTN levels likely enhance cells’ antiviral defense, while reduced OPTN levels compromise their ability to fight infections." (PMID 38019030, 2023). "To determine if the increased IFN response in OPTN KO cells during infection depends on TBK1 expression, we silenced TBK1 in OPTN KO cells." (PMID 38019030, 2023). "Precise insights into OPTN’s interactions with TBK1 during infection, both in its presence and absence, remain elusive." (PMID 38019030, 2023). "Compared to control, the apoptosis of cells expressing Tau-P301L significantly increased at 72 h after infection, which was reduced by OPTN expression." (PMID 35662233, 2022). "During infection by CNF1-producing uropathogenic E. coli, OPTN is required for efficient bacterial invasion and associated mechanochemical reinforcement of integrins." (PMID 36229487, 2022). "Having shown that CNS infection leads to neuron death, and IFNγ was highly represented in multiple tissues of Optn−/− mice, we sought to understand the role of OPTN in necroptosis during infection." (PMID 34518549, 2021). "When TBK1 was inhibited using BX795, both the total level of OPTN and the phosphorylated form were decreased in an infection independent manner suggesting that OPTN function is constitutively regulated by TBK1." (PMID 34518549, 2021). "While OPTN deficiency resulted in increased infection by wildtype HSV-1, infection with a γ134.5 null mutant of HSV-1 resulted in equal levels of infection between both genotypes." (PMID 34518549, 2021). "Co-immunoprecipitation of OPTN showed that upon infection OPTN first interacted with TBK1, and then with VP16." (PMID 34518549, 2021). "We have shown in HCE cells and LUHMES differentiated into neurons that OPTN knockdown leads to enhanced infection." (PMID 34518549, 2021). "In parallel, we performed time-course infections in HeLa cells overexpressing exogenous Flag-tagged OPTN or GFP-tagged T6BP." (PMID 34149637, 2021). "Upon infection of cells with Salmonella, OPTN associates with ubiquitin-coated bacteria and recruits TBK1 that phosphorylates OPTN, enhancing its LC3 binding affinity, through which it promotes the autophagic clearance of bacteria." (PMID 29692786, 2018). "The infection of OPTN siRNA-transfected cells with another RNA virus, such as the vesicular stomatitis virus, to activate the RLRs, yielded similar results." (PMID 27538435, 2016). "Following infection with Sendai virus, leading to RLR activation, an increase in the association of TBK1 with OPTN was detected and p-TBK1S172 was found in complex with OPTN in the Golgi-enriched fraction." (PMID 27538435, 2016). "To determine the importance of OPTN in host antibacterial response, we employed models of infection in two evolutionarily divergent species." (PMID 26044960, 2015). "To determine the importance of OPTN in antibacterial response across species, we performed preliminary experiments in a zebrafish infection model involving Salmonella enterica." (PMID 26044960, 2015). "Infection of HeLa cells with the adenoviruses expressing shRNAs (Ad-shOptn1 and Ad-shOptn2) resulted in 70-80% decrease in optineurin protein level, as determined by western blotting." (PMID 20085643, 2010).
infection (continued). "Optineurin had an inhibitory effect on IFNβ reporter activation after infection with BUNdelNSs, whereas the D474N mutant that was incapable of binding to ubiquitin did not." (PMID 20174559, 2010). "Interestingly, we did observe a higher expression of MLKL in OPTN ‒/‒ cells at 2 and 4 h post‐infection." (PMID 40490945, 2025). "Although the infection levels differed in OPTN and TBK1 deficient cells, in this series of experiments, we aimed to evaluate whether TBK1 and OPTN work collectively to trigger an IFN response against HSV-1." (PMID 38019030, 2023). "However, the decrease in OPTN levels was partially rescued by Δγ134.5 and ΔUL46 infections, suggesting a potential interaction between these proteins and OPTN." (PMID 38019030, 2023). "Thus, this RNA virus prevents OPTN from activating TBK1 as part of a strategy to modulate the innate immune response to facilitate its replication after infection." (PMID 27538435, 2016). "Infection of HeLa cells with adenoviruses expressing shRNAs (Ad-shOptn1 and Ad-shOptn2) resulted in significant decrease in optineurin protein level after 72 hours of infection, as determined by western blotting; however there was no significant change in the level of IκBα or NF-κB p65." (PMID 19340308, 2009). "We found that protein levels of endogenous as well as exogenous OPTN were stable during early phase of CVB3 infection and slightly decreased upon infection." (PMID 34149637, 2021). "OPTN is regulated by TBK1 during infection, as inhibition of TBK1 inhibits the expression and phosphorylation of OPTN during HSV-1 infection." (PMID 34518549, 2021). "In contrast, later during infection, when polyubiquitin has accumulated on cytosolic bacteria, other cargo receptors, including SQSTM1/p62 and OPTN (optineurin), also contribute." (PMID 31258038, 2019). "Conversely, cells that were depleted of optineurin by treatment with siRNA were more resistant to SeV and SFV infection, and these cells produced more IFNβ upon infection." (PMID 20174559, 2010). "We did not observe changes in MLKL expression in the presence or absence of OPTN at 6 h post‐infection, but there was upregulation of MLKL 24 h post‐infection in Optn ‒/‒ HCE cells." (PMID 40490945, 2025). "However, the microscopy images of OPTN KO and TBK1 KO cells infected with HSV-1 revealed an unexpectedly higher spread of infection in OPTN KO cells compared to the TBK1 KO cells." (PMID 38019030, 2023). "HCE, but not LUHMES, cells showed significantly more HSV-1 17 strain infection when OPTN was knocked down." (PMID 34518549, 2021). "Despite the role of OPTN in reducing HSV-1 protein expression and restricting spread of infection, OPTN does not affect the total level of autophagy within cells during infection of the knockdown or knockout in vitro models." (PMID 34518549, 2021). "Four receptors (BNIP3L, Optineurin, FUNDC1, and TAX1BP1) were selectively modified upon Mtb infection; these modifications occurred in functional domains of these receptors and changed through the time course of infection." (PMID 31951200, 2020). "We report that in addition to NDP52/CALCOCO2 and OPTINEURIN/OPTN, another autophagy receptor, namely T6BP/TAXIBP1, also regulates the maturation of autophagosomes by promoting their fusion with lysosomes, independently of any infection." (PMID 28531150, 2017). "Notably, protein levels of OPTN are not altered during early infection and slightly reduced upon late infection." (PMID 34149637, 2021). "Together this data suggests that OPTN is a constitutively active antiviral defense factor that suppresses the expression of autophagy degradable essential viral proteins without changes to the total level of autophagy during infection." (PMID 34518549, 2021). "This function of OPTN does not affect the total level of autophagy in HeLa or LUHMES cells as is reflected by the lack of increased or decreased LC3 lipidation, the process by which LC3 is recruited to autophagosomal membranes, during infection." (PMID 34518549, 2021).
cancer (24 papers, 2009 to 2025). A tumor composed of atypical neoplastic, often pleomorphic cells that invade other tissues. "The positive correlations between the expression of PINK1, SRC, BECN1, and OPTN and drug sensitivity suggest that higher levels of these genes are associated with increased vulnerability of cancer cells to treatment." (PMID 39859167, 2025). "During CRC progression from adenoma to invasive carcinoma, OPTN expression is gradually lost, which is associated with an increased ability of cancer cells to evade immune detection." (PMID 41294799, 2025). "Given its role in these critical processes, dysregulation of OPTN has been linked to various diseases, including neurodegenerative disorders, cancer, and inflammatory conditions, making it an important target for further research and therapeutic intervention." (PMID 41294799, 2025). "Conversely, OPTN has also been implicated in cancer progression, with its expression levels varying across different malignancies." (PMID 41294799, 2025). "Besides its role in xenophagy, OPTN has been identified as a primary autophagy receptor that translocates to the mitochondria during mitophagy and has been implicated in cancer and neurological disorders." (PMID 34578425, 2021). "Dysfunction in OPTN structure, whether through mutations or altered expression levels, has been implicated in various diseases, including neurodegenerative disorders and cancer." (PMID 41294799, 2025). "Furthermore, we uncovered significant enrichment of immune cell infiltrates associated with OPTN in different cancer types, highlighting the complex regulatory mechanisms involved in cancer pathogenesis, which entail an intricate interplay between genetic mutations and immune cell interactions." (PMID 39859167, 2025). "Despite its significance in oncogenic pathways and immune regulation, the therapeutic potential of targeting OPTN in cancer remains largely unexplored." (PMID 41294799, 2025). "Taken together, these observations highlight that while OPTN represents a biologically significant and potentially druggable target in cancer, its multifaceted physiological functions demand extreme caution in therapeutic targeting." (PMID 41294799, 2025). "Given its multifaceted roles in autophagy, cellular signaling, and immune regulation, OPTN emerges as a compelling target for therapeutic intervention in cancer." (PMID 41294799, 2025). "Given its diverse cellular roles as a multifunctional regulator in autophagy, vesicular trafficking, and immune signaling, OPTN represents a compelling yet complex target in cancer therapy." (PMID 41294799, 2025). "We delved into the molecular mechanisms by which LC3, PINK1, PRKN, SRC, BNIP3L, BECN1, and OPTN regulate mitophagy, cancer progression and drug sensitivity or resistance." (PMID 39859167, 2025). "Overall, the Spearman’s correlation coefficients varied across different cancer types, revealing distinct patterns of immune cell correlation with the expression of OPTN, PINK1, MAP1LC3A, PRKN, BNIP3L, BECN1, and SRC." (PMID 39859167, 2025). "This review aims to provide a comprehensive understanding of OPTN’s pleiotropic functions, highlighting its role in autophagy, inflammation, immune surveillance, and cancer progression." (PMID 41294799, 2025). "This review aims to provide a comprehensive examination of the structural and functional aspects of OPTN in cancer, highlighting its diverse roles across autophagy, tumorigenesis, and immune modulation." (PMID 41294799, 2025). "We then explored the methylation levels (beta-values, HumanMethylation450) of MAP1LC3A, OPTN, PINK1, PRKN, SRC, BNIP3L, and BECN1 in pan-cancer and their association with gene expression and the immune cell infiltrates." (PMID 39859167, 2025). "Given its integral role in autophagy, OPTN can either support tumorigenesis by fueling cancer cell metabolism or act as a suppressor by mitigating cellular stress and oxidative damage." (PMID 41294799, 2025).